IL6 (interleukin 6)
Diseases named in the same sentence as IL6 in open-access papers (continued):
Sharing a sentence is not in itself a finding about the gene and the disease.
malaria (continued). "Consistent with this, levels of TNF-α, IL-10 and IL-6 in placental blood (but not peripheral blood) were inversely correlated with peripheral Apo-AI levels in malaria-infected primigravidae (r = −0.385, p = 0.0017, n = 67; r = −0.484, p = 0.0002, n = 62; r = −0.353, p = 0.025, n = 50 respectively)." (PMID 20098675, 2010). "This directly infers IL-6 blockade by malarial CSP prevents immediate protective T cell activation and memory responses in the skin, LN and infected hepatocytes, simultaneously stimulating in these locations antigen-specific Treg formation and expansion, triggered by malaria antigens." (PMID 20502667, 2010). "Children who have blood smear detectable malaria have been found to have higher levels of IL-6, compared with children who do not have blood smear detectable malaria infections and circulating IL-5 levels were elevated in children who had detectable S. mansoni eggs." (PMID 19149774, 2009). "In P. vivax infection, maternal plasmatic cytokine imbalance may have an impact on pregnancy outcomes, as indicated by the positive correlation between both IL-6 and IL-10 levels with previous exposure to malaria and parasitemia, as well as a negative correlation with gestational age at delivery." (PMID 39495782, 2024). "The proinflammatory cytokines: TNF‐α (p < .001), IFN‐ɣ (p < .001), IL‐1β (p < .001), IL‐6 (p < .001), GM‐CSF (p < .001), and the anti‐inflammatory cytokine IL‐10 (p < .001) levels were significantly higher in malaria‐infected males and females than in their counterparts without malaria." (PMID 39240033, 2024). "Among both children less than 5 years, and those from 5 to 12 years, TNF‐α (p < .001), IFN‐ɣ (p < .001), IL‐1β (p < .001), IL‐6 (p < .001), GM‐CSF (p < .001), and IL‐10 (p < .001) levels were elevated in the participants with malaria compared with the apparently healthy children without malaria." (PMID 39240033, 2024). "However, for the malaria group, four distinct correlation patterns were observed; first pattern (CCL4, CCL2, CCL3, IL12 and IL2), second pattern (IL-17A, IL-1β, CCL11, IL4), third pattern (IL5, IL7, IL13), and fourth pattern (IL1RA, CXCL10, TNFα, IL2R, CXCL9, IL6)." (PMID 35811678, 2022). "Malaria-naïve adults and children from low-transmission regions tend to generate strong pro-inflammatory responses: TH1 cytokines IFN-γ and TNFα, and other pro-inflammatory cytokines such as IL-1β and IL-6, are produced, which may favor generation of TH1-like responses." (PMID 31156642, 2019). "Similarly, IL-8, IL-6, IL-15 and MCP-1 were reported as increased during malaria." (PMID 27168977, 2016). "The frequency of SNPs in DDX39B (-22C > G and -348C > T), TNF (-308G > A) and IL6 (-176G > C) were compared between P. vivax-infected study participants who exhibited different clinical outcomes, including asymptomatic infection, mild malaria, complicated malaria, and no infection." (PMID 25038626, 2014). "While increased IL-6 and IFN-γ levels have been reported in malaria, we found a negative correlation between these cytokines and platelet counts." (PMID 40690473, 2025). "In patients with severe malaria, platelets showed negative correlations with CXCL10, IL-6, IL-10 and IFN-γ." (PMID 36178979, 2022). "We first assessed circulating cytokine (IL-6, IL-10, TNF-α, IFN-3γ) concentrations among healthy participants with- and without asymptomatic malaria and patients with clinical malaria." (PMID 34177883, 2021). "The absence of IL-1β and IL-6 and TNFα during CHMI is not unusual as reported in other controlled malaria studies." (PMID 34548530, 2021). "Despite that, in participants with symptomatic malaria, the degree of CCL2 perturbation exhibited two negative correlations, vs. IL-6 and TNF-α." (PMID 34727121, 2021). "Significant correlations were identified for select individual genotypes with and without malaria between CXCL10, TNF-α and IL-6 with Hb, WBC, and RBC." (PMID 33424841, 2020).
malaria (continued). "Although P. vivax and P. falciparum malaria patients have similar cytokine profiles during infection, in P. vivax acute phase malaria, APRIL but not BAFF levels correlated positively with IL‐1, IL‐2, IL‐4, IL‐6, and IL‐13 levels." (PMID 29314720, 2018). "In a separate study in Malawian children, those presenting with severe malaria had higher levels of IL-6 and TNF-α than did those presenting with UCM, although severe malaria was not further subcategorized." (PMID 28122790, 2017). "In contrast to TNFα, IL-6, IL-8, IL-15 and MCP-1, eotaxin was not often mentioned in previous malaria studies." (PMID 27168977, 2016). "The lack of difference in the levels of IL-6 and CXCL-8 according to the number of malaria episodes was expected since they are biomarkers produced by cells from the innate immune system." (PMID 24741587, 2014). "Nevertheless, immigrants and travelers with malaria had higher IFN-γ, IL-6 and IL-10 compared to those without malaria." (PMID 23967342, 2013). "Of seven cytokines analyzed in this study, IL-6, IL-10 and IFN-γ were elevated in malaria patients sera, thrombocytopenic or not, compared to HVs." (PMID 23723981, 2013). "The assayed cytokines were detectable in the placental sera (IFN-γ, IL-12, IL-4, IL-6 and IL-10) and plasma (TNF-α) samples extracted from malaria-infected and malaria-negative olive baboons." (PMID 26623293, 2012). "However, levels of TNF‐α,10 IL‐1β,16 IL‐6,8, 33 IFN‐ɣ,33 IL‐10,11, 33 and GM‐CSF27 were not different when malaria‐infected children were compared to their counterparts without the infection in previous studies." (PMID 39240033, 2024). "Furthermore, we previously showed that different sickle Hb genotypes with or without malaria parasites have different levels of CXCL10, CCL3, IL-8, TNF-α, and IL-6 in the blood." (PMID 37108709, 2023). "Whole blood from asymptomatic participants with and without positive malaria microscopy were ex-vivo stimulated with S. aureus, E. coli LPS and Salmonella Typhimurium; cytokine concentrations (TNF-α, IFN-γ, IL-1β, IL-6, IL-10) were measured on supernatants using ELISA." (PMID 34177883, 2021). "Malaria infection in the collected maternal peripheral, placental, umbilical cord samples was determined microscopically, and ELISA was used to measure the plasma levels IL-4, IL-6, IL-10, IL-17A, and INF γ in the collected positive and negative malaria samples." (PMID 33422078, 2021). "Participants with asymptomatic malaria had also lower IFN-γ and IL-10 responses after Salmonella Typhimurium stimulation, while monocyte cytokines (IL-1β, IL-6, TNF-α) were not statistically different between slide negative participants and participants with asymptomatic malaria." (PMID 34177883, 2021). "Indeed, our findings showed that, in P. vivax acute phase malaria, APRIL but not BAFF levels correlated positively with IL‐1, IL‐2, IL‐4, IL‐6, and IL‐13 levels." (PMID 29314720, 2018). "Here we found that Malawian children presenting with all forms of malaria had high IL-10-to-TNF-α and IL-10-to-IL-6 ratios, so high levels of TNF-α and IL-6 in CM could not be attributed to a lack of IL-10 response." (PMID 28122790, 2017). "We measured plasma levels of soluble UA and inflammatory cytokines and chemokines (IL-6, IL-10, sTNFRII, MCP-1, IL-8, TNFα, IP-10, IFNγ, GM-CSF, IL-1β) in 470 Malian children presenting with uncomplicated malaria (UM), non-cerebral severe malaria (NCSM) or cerebral malaria (CM)." (PMID 23071567, 2012).
ulcerative colitis (239 papers, 2010 to 2025). An inflammatory bowel disease involving the mucosal surface of the large intestine and rectum. "Balsalazide shows promise in inhibiting ulcerative colitis-related carcinogenesis through IL-6/STAT3 signaling pathway, though it has been linked to pericarditis in some studies." (PMID 39444551, 2024). "Further study found that high expression of IL6 was common in patients with Crohn's disease and ulcerative colitis and was closely associated with disease activities." (PMID 36371157, 2022). "Serum inflammatory markers such as TNF-α, IL-6 and IL-1β are often considered as hallmark of ulcerative colitis." (PMID 36159798, 2022). "In an ulcerative colitis (UC)-associated mouse model, β-carotene supplementation at 20 mg/kg body weight (BW)/day for 28 days significantly reduced colonic IL-6 and TNF-α levels, which was in line with our findings." (PMID 34646849, 2021). "As a result, this research utilized 11 serotonin derivatives to assess the effect of NO on LPS-stimulated RAW 264.7 cells and its role in regulating crucial cytokines linked to ulcerative colitis, specifically IL-6, TNF-α, IL-1β, and IL-10, through Griess and RT-qPCR assays." (PMID 40649400, 2025). "Moreover, elevated levels of IL-6 were associated with prolonged orocecal transit in ulcerative colitis." (PMID 37189645, 2023). "FMT is also associated with lower serum IL-6 levels in patients with ulcerative colitis, indicating that this procedure may alleviate inflammatory diseases by reducing inflammatory cytokine production." (PMID 35783298, 2022). "It amplifies inflammation by activating other cells, by upregulating some cytokines (Il-1β and IL-6) and by stimulating NF-κB—an indispensable pathway in ulcerative colitis pathogenesis." (PMID 41010030, 2025). "A pilot study showed a decrease in serum levels of tumor necrosis factor‐alpha TNF‐α, interleukin IL‐6 and IL‐8 in ulcerative colitis patients in remission who received sprouted barley." (PMID 40432400, 2025). "This shift reduces pro-inflammatory cytokines (TNF-α, IL-1β, IL-6), elevates anti-inflammatory IL-10, and mitigates mucosal damage, positioning miR-223 as a potent therapeutic candidate for ulcerative colitis (UC)." (PMID 40799643, 2025). "For example, obefazimod (ABX464), a small molecule that modulates the splicing of lncRNA 0599-205 to enhance miR-124 expression, has shown efficacy in late-phase clinical trials for ulcerative colitis, leading to suppression of IL-6 and IL-17A pathways." (PMID 40981386, 2025). "IL-6 is a key inflammatory mediator that increases epithelial permeability, promotes macrophage infiltration and worsens ulcerative colitis, mainly by modulating the balance between Th17 and Treg cells." (PMID 41010030, 2025). "sgp130Fc, a selective inhibitor of IL-6 trans-signaling, is undergoing clinical evaluation for ulcerative colitis (UC) and shows therapeutic promise in lung diseases." (PMID 40969747, 2025). "Elevated intestinal levels of the inflammatory cytokine IL-6 are positively correlated with the activity and severity of ulcerative colitis." (PMID 40443529, 2025). "A milk-based fruit drink enriched with phytosterols blocked oxidative stress and reduced interleukin (IL)-8 and IL-6 levels in differentiated Caco-2 cells and exhibited anti-inflammatory activities in an experimental mouse model of chronic ulcerative colitis." (PMID 38337729, 2024). "IL-6 is closely related to inflammatory responses, intestinal inflammatory responses, and ulcerative colitis." (PMID 37246319, 2024). "IL-6 trans-signaling-specific inhibitor olamkicept has been developed for treating ulcerative colitis with promising results in phase II clinical trials." (PMID 39749325, 2024). "Previous studies have shown that TNFα and IL6 increase in patients with ulcerative colitis, and deletion of TNFα or IL16 reduces CAC in murine models." (PMID 37810110, 2023).
ulcerative colitis (continued). "Previous studies, however, have demonstrated that IL-6 level was elevated in a mouse model of DSS-induced ulcerative colitis and blood of IBD patients." (PMID 36457188, 2023). "GGQLD has been shown to alleviate ulcerative colitis by inhibiting the IL-6/JAK2/STAT3 signal transduction pathway and restoring the homeostasis of Th17 and Treg cells within colon tissues." (PMID 37370132, 2023). "In animal models of hepatocytic and aortic inflammation and ulcerative colitis, FA treatment inhibited the production of the inflammatory cytokines IL-6, IL-1, and TNF-α." (PMID 37371967, 2023). "Our results exhibited significant increases in FC and CRP, IL-6, AOPPs, MTs, and p53Abs in ulcerative colitis patients with parasitic infections compared to those without parasites." (PMID 37710023, 2023). "COST reduced the inflammatory response in mice with ulcerative colitis by lowering the proinflammatory cytokines IL-1β, IL-6, and TNF-α." (PMID 37736519, 2023). "A previous study reported that Oscillibacter was increased in mice with ulcerative colitis (UC) and was significantly positively correlated with IL-6 and IL-1β levels." (PMID 36786568, 2023). "Whereas, increased IL‐6 expression exacerbates the inflammatory response of macrophages through the JAK1/STAT3 pathway in mouse models of ulcerative colitis." (PMID 36794521, 2023). "Aspirin markedly reduced interleukin-6 and enhanced interleukin-10 compared to the ulcerative colitis model group (P < .05) induced Azoxymethane/dextran sulfate sodium inflammation (3 weeks) and atypical hyperplasia (8 weeks)." (PMID 35946886, 2022). "As a pro-inflammatory cytokine, TNF-α and IL-6 play important roles in the pathogenesis of ulcerative colitis." (PMID 36171753, 2022). "A total of 4 literatures measured the improvement of ulcerative colitis by the levels of inflammatory factors (IL-6, TNF-α, and CRP)." (PMID 35912148, 2022). "miR-214 overexpression was also found to induce an inflammatory response in the ulcerative colitis experimental model by promoting NF-kB phosphorylation and subsequently IL6 expression through PTEN and PDZ-LIM domain-containing protein 2 (PDLIM2) inhibition." (PMID 36291876, 2022). "Our study also further confirmed the important role of inflammatory factors, such as NO, TNF-α, IL-1β and IL-6, in the occurrence and development of ulcerative colitis." (PMID 35163182, 2022). "Interleukin-6 was increased and interleukin-10 was decreased in mice of ulcerative colitis model group compared with the control group (P < .05)." (PMID 35946886, 2022). "Serving as a vital inflammation pathway, IL-6/STAT3 signaling pathway had been reported to be activated to trigger inflammatory response of the body in ulcerative colitis." (PMID 34722512, 2021). "Baicalin can significantly reduce the serum interleukin-17 (IL-17), IL-6, and IL-1β expression in Ulcerative Colitis (UC) rats." (PMID 34692749, 2021). "Our study is in agreement with a recent study that reported that nifuroxazide reduced colon ulcer in an acetic acid-induced ulcerative colitis model via modulating the IL-6/STAT-3/Wnt axis." (PMID 34833950, 2021). "TNF-α, IL-1β and IL-6 are the cytokines which play pro-inflammatory roles in the process of ulcerative colitis." (PMID 34604183, 2021). "Another aspect that is worth noting is that systemic LPS induces the expression of IL-6 and other inflammatory cytokines, which can promote Crohn’s disease and ulcerative colitis." (PMID 34200555, 2021). "IL-6 plays an important role in the occurrence and development of ulcerative colitis, and its expression can reflect the degree of inflammation of ulcerative colitis." (PMID 34348654, 2021). "In particular, LPS activates pathways that are directly involved in the progression of Crohn’s disease and ulcerative colitis, particularly the NF-κB pathway, which increases levels of IL-1, IL-6, and TNF-α, among others." (PMID 34200555, 2021).
ulcerative colitis (continued). "Jak3 knockout mouse model showing Il-2, Il-4, Il-7, Il-9, and Il-15 conduction defects, elevated levels of Il-6 and Il-17a and severe immunodeficiency, defects in barrier function lead to Ulcerative colitis (UC)." (PMID 33777833, 2021). "Suppression of IL-1β and IL-6 inflammatory markers in macrophages, and dependent-protection against ulcerative colitis." (PMID 33868227, 2021). "The typical feature of ulcerative colitis was the inflammation of the intestinal mucosa, which resulted from the activation of the immune response by pro-inflammatory mediators (IL-6 and TNF-α) and anti-inflammatory cytokine IL-10." (PMID 35010176, 2021). "The inflammatory cytokines, including TNF-α, IL-1β and IL-6, were also suppressed and the percentages of macrophages were decreased, after using a kind of anti-ulcerative colitis medicine in CAC." (PMID 33201893, 2020). "Both AAs cause a reduction of interleukin 6, 8 and TNFα levels, and their serum levels appear to be decreased in human with IBD and ulcerative colitis." (PMID 32321505, 2020). "In particular, fecal levels of IL-6, IL-8 and IL-1β are elevated in the context of acute bacterial or viral gastroenteritis and ulcerative colitis." (PMID 32909002, 2020). "Hesperidin, a component of Pericarpium Citri reticulatae, can ameliorate dextran sulfate sodium-induced ulcerative colitis in mice and reduce the amount of mucosal damage, myeloperoxidase, malondialdehyde activities, and serum IL-6 levels." (PMID 33817258, 2020). "Oscillibacter abundance was considerably positively related to IL-1β and IL-6 expressions and ulcerative colitis pathological scores in mice." (PMID 33178314, 2020). "A high IL-10 serum level is maintained during the early phase of remission in some human ulcerative colitis patients, whereas C-reactive protein and IL-6 serum levels return to normal during remission after an increase during the acute phase." (PMID 31244763, 2019). "Studies have shown that levels of the pro-inflammatory cytokines, IL-1β and IL-6, are predictably increased in the mucosa of patients with Crohn's disease and ulcerative colitis." (PMID 31749791, 2019). "Lamina propria mononuclear cells isolated from colonic biopsies from ulcerative colitis and Crohn's disease patients released high levels of IL-6 when compared to control subjects." (PMID 30356663, 2018). "Significant decreases were seen in the levels of IFN-γ, IL-1β, and IL-6, all of which are elevated in human lamina propria mononuclear cells isolated from ulcerative colitis and Crohn's disease patients." (PMID 26457007, 2015). "Interleukin-6 is a pro-inflammatory cytokine which is markedly elevated in various inflammatory diseases of the gut, including Crohn's disease, ulcerative colitis, and necrotizing enterocolitis." (PMID 24662742, 2014). "Activated macrophages and neutrophils secrete proinflammatory cytokines such as TNF-α, IL-1β, and IL-6 to regulate the inflammatory response in the colonic mucosa of patients with ulcerative colitis." (PMID 24971344, 2014). "Specifically, increased levels of TNF-α, IL-1β, IFN-γ, IL-6, and IL-8 have been reported in ulcerative colitis patients." (PMID 23630633, 2013). "Along with the paracellular leakage of monomeric IgA and IgG antibodies, other serum-derived or locally produced factors and mediators will also appear in whole saliva such as IL-6 in patients with ulcerative colitis." (PMID 23487566, 2013). "The hyper-activation of immune cells involved in the pathogenesis of ulcerative colitis, known to produce high levels of pro-inflammatory cytokines such as IL-6." (PMID 24451125, 2013). "L. plantarum K68 (K68), a probiotic strain isolated from fu-tsai, has been shown to reduce the production of pro-inflammatory cytokines (TNF-α, IL-β, and IL-6) in dextran sulfate sodium (DSS)-induced ulcerative colitis BALB/c mice." (PMID 23690866, 2013).